PARP1 (poly(ADP-ribose) polymerase 1)
Diseases named in the same sentence as PARP1 in open-access papers (continued):
Sharing a sentence is not in itself a finding about the gene and the disease.
tumor (continued). "As a key repair enzyme, PARP-1 ensures the stability of a tumor cell genome after treatment with DNA damaging chemotherapy agents." (PMID 34768872, 2021). "PARP1 was found to be a cofactor for adenovirus E2 promoter-binding protein (E2F-1), a transcription factor with dual oncogene or tumor suppressor functions and abilities to control the balance between proliferation and cell apoptosis." (PMID 33572647, 2021). "Together, these results indicated that upregulation of PARP1 in SCC11A cells adequately conferred tumor cell resistance to chemotherapeutic drugs." (PMID 35071239, 2021). "PARP-1 is also known to control the expression of heat shock protein 70, which makes a significant contribution to the survival of tumor cells and their resistance to antitumor agents." (PMID 34768872, 2021). "In osteosarcoma tumor cells, PARP1 has been found to co-activate oncogenic transcription factor B-MYB." (PMID 34686201, 2021). "Evaluation of transcript–protein correlations by the tumorsubgroup revealed that ∼25% of the transcript–proteinpairs often displayed radically different correlations dependent onthe ER status (e.g., PARP1) or tumor appearance (e.g., MMP2)." (PMID 33855848, 2021). "Moreover, loss of PARP-1 in mouse models may decrease tumor development." (PMID 33572586, 2021). "Analysis of SYO.1 tumor lysates showed increased cleavage of PARP1 and caspase 3 in the combination group compared to the vehicle or single-agent groups." (PMID 34065859, 2021). "In the current study, we revealed a significant correlation between the high expression of PARP1 and localization of the primary tumor in the head and neck region (vs. trunk and extremities)." (PMID 33572647, 2021). "Of note, we have previously demonstrated that dual deficiency for PARP-1 and PARP-2 in T cells results in a significant decrease of both CD4 and CD8 peripheral T cells and consequently impairs the T cell response to tumours." (PMID 34885119, 2021). "In combination with a potent PARG inhibitor, the enhanced PARP1 activation triggers selective tumor cell apoptosis, with little effect on normal cells such as astrocytes." (PMID 34806016, 2021). "However, a systematic analysis of the prevalence and predictive value of PARP1 alteration for ICI therapeutic effectiveness in multiple tumor types remains largely unknown, and the associations between its expression levels and immunotherapy-associated signatures also need to be explored." (PMID 34531868, 2021). "This implicates PARP1 in both tumour development, by ERK2 stimulation resulting in tumour growth, and in tumour progression, through metastasis by PARP1’s pro-inflammatory effects, as a result of its interaction with the NF-κB pathway." (PMID 34440228, 2021). "PARP1 modifies HuR, which at least partly, accounts for the elevated HuR oligomerization/multimerization observed in tumor cells, thereby promoting the stabilization of tumor-associated factor mRNAs." (PMID 32789690, 2021). "PARP-1 is involved in the process of epithelial-mesenchymal transition (EMT) during the acquisition of the ability of tumor cells to metastasize." (PMID 34768872, 2021). "This treatment-induced PARP1 expression can potentially serve as a prognostic biomarker that predicts both tumor resistance to DNA damaging agents, and therapeutic benefits of PARPi in combination therapy." (PMID 35071239, 2021). "Higher PARP1 expression was present in 27 tumor compared the corresponding normal tissues using the GTEx and TCGA databases and it had a worse OS in several tumors (P < 0.05)." (PMID 34531868, 2021). "Consistent with the established function of PARP1 in DNA repair, we showed that overexpression of PARP1 rendered the primary tumor cells highly resistant to DNA damage treatment." (PMID 35071239, 2021). "At early stages, PARP1 is thought to play an anti-tumour role in CRC by repairing DNA damage that would otherwise result in mutagenesis." (PMID 34440228, 2021).
tumor (continued). "Previous studies proved that the suppression of PARP1 can inhibit the repair process of DNA damage, thus enhancing the sensitivity of the tumor to chemoradiotherapy." (PMID 33495407, 2021). "This is supported by the increased PARP1 mRNA expression demonstrated in tumour samples, compared to surrounding matched normal tissue." (PMID 34440228, 2021). "By analyzing oral tumor cells derived from the primary and recurrent tumors of the same patient, our study revealed upregulated PARP1 expression in the recurrent tumor cells." (PMID 35071239, 2021). "Tumor regions displayed significantly higher PARP1 expression compared to deep margin and epithelium." (PMID 34194286, 2021). "Here we will only briefly describe the effect of PARP-1 on tumor cell metabolism, referring readers to the published reviews for more details." (PMID 34768872, 2021). "Taken together, our studies reported PARP1 upregulation as a clinically relevant mechanism of tumor resistance, and suggested PARPi as promising therapeutic intervention, in combination with chemotherapy." (PMID 35071239, 2021). "The pro-tumor activity of PARP-1 is mediated by PARP-1-dependent deregulation of factors involved in the cell cycle, mitosis, apoptosis and autophagy." (PMID 34768872, 2021). "We found the co-occurrence of genetic mutations in tumors with PARP1 alterations to be involved with some genes such as KMT2D/2C as driver genes, PIK3CA, ARID1A, H3F3A, HIST3H3, RYR2, and thus, PARP1 alteration should promote tumor mutability." (PMID 34531868, 2021). "In order to evaluate the expression of PARP1, 3-5 fields of view from three tissue sites were randomly selected, deep margin (submucosa, muscle tissue), epithelium, and tumor, from the H&E and IHC scan of entire tissue for quantification." (PMID 34194286, 2021). "Together, we find that treatment of NRH, to acutely raise cellular NAD+ levels, supports robust PARP1 activation in GSC/tumor cells in response to replication stress." (PMID 34806016, 2021). "Among the Pirh2-interacting proteins were the ones that are involved in gene expression regulation, DNA repair, apoptosis, and tumor transformation (e.g., PARP1, ku70, Sirt1, HuR, and Dicer)." (PMID 34091597, 2021). "In contrast, tumor growth is accompanied by a moderate activation of PARP-1 that supports survival of tumor cells due to enhancement of DNA lesion repair and resistance to therapy by DNA damaging agents." (PMID 34768872, 2021). "Poly(ADP-ribose) polymerase-1 (PARP)-1 can promote tumor growth and progression through DNA repair activity." (PMID 33671196, 2021). "PARP1 expression was evaluated by immunohistochemistry performed on 128 whole tumor slides from archival formalin-fixed, paraffin-embedded specimens." (PMID 33572647, 2021). "Drugs targeting PARP-1, such as olaparib, impair the DDR, and sensitize tumor cells to other treatments that cause DNA damage, such as radiation therapy." (PMID 34195200, 2021). "This is the case with tumours associated with mutations in one copy of either BRCA1 or BRCA2; in these tumours, PARP1/2 inhibitors lead to an accumulation of DNA SSBs, which are converted during replication to irreparable toxic DNA double-strand breaks." (PMID 33050515, 2020). "It was determined to have both good in vitro cellular potency (IC50 for PARP-1 inhibition of 6 nM) and in vivo efficacy because it led to 80% tumor inhibition when fed in combination with temozolomide to mice." (PMID 33233320, 2020). "[18F]AZD2461 was taken up in vivo in PARP1-expressing tumours, and the highest uptake was observed for PSN-1 cells (7.34 ± 1.16 %ID/g)." (PMID 32342268, 2020). "Not surprisingly, all mice transplanted with Parp1+/+ cRb−/−RasV12 cells developed tumours, while tumours were detected in only 3 out of 12 mice injected with Parp1−/− cRb−/− RasV12 cells." (PMID 33050515, 2020). "Twenty of 24 available FFPE tumor samples were immunohistochemically evaluable for PARP1 expression." (PMID 33142760, 2020).
tumor (continued). "Results demonstrated that vimentin, P-akt, and P-s6k were up-regulated in BC tissues, while expression of N-Cadherin, P-mTOR, p62, and PARP1 were decreased in tumor." (PMID 33424916, 2020). "At the same time, decreased Ki-67 was observed in the tumor section, and increased cleaved PARP1 and caspase-3 was found in siRNA-1 exosome injection group." (PMID 32951010, 2020). "Though this can lead to an overestimation of tumor size by imaging tracers, the high PARP1 levels in the tumor microenvironment can enhance theranostic tracer uptake leading to better therapeutic efficacy." (PMID 32640708, 2020). "Caspase 3 (and its cleavage CC3) is the central member of the caspase family, which is cleaved into 29- and 85-kDa fragments by PARP-1 during the early stages of apoptosis, mediating tumour repopulation in apoptotic tumour cells." (PMID 32895397, 2020). "There is strong evidence in support of the concept that hypoxia increases both the expression and the activity of PARP-1, contributing to tumor malignancy." (PMID 32286485, 2020). "The influence of LC staging in the PARP protein expression levels found in tumor specimens of all of the patients taken as a whole, revealed that patients in stage I exhibited the greatest amount of PARP-1 expression compared to the other LC stages." (PMID 33187221, 2020). "PARP inhibitors synergistically interact with ATM inhibitors by blocking firing of the replication fork and sensitizing tumor cells to PARP1 trapping, which leads to DNA damage and tumor cell death." (PMID 33324554, 2020). "It has been reported that oxidative stress-induced apoptosis of CD8 T cells is mediated through PARP1 activation; possibly the mechanism is being exploited by tumor cells to evade the anti-tumor immune response." (PMID 32709019, 2020). "Since PARP1 is known to influence both tumour vasculature and gene transcription in immune cells, exploratory assessment of serum immune-related and angiogenesis biomarker concentrations over time was assessed." (PMID 32523090, 2020). "The immunohistochemical analysis showed that the levels of PD-L1 and p-STAT3 (Tyr705) were increased, while that of PARP1 was decreased in tumor tissue samples from mice treated with ODN1585 alone or in combination with an anti-PD-1 antibody." (PMID 32483468, 2020). "By comparison, such knockouts had minimal effects on tumor cell responses to inhibitors of PARP1 (Olaparib) or CBP of the Wnt pathway (ICG001)." (PMID 33006750, 2020). "PARP-1 subcellular localization on the chromatin provides an ideal target for tumor cell specific delivery of Auger emitters to DNA." (PMID 33352773, 2020). "Our results demonstrate that genetic ablation of Parp1 extends the survival of Rb-null embryos, while genetic inactivation of Parp1 results in reduced development of pRb-dependent tumours." (PMID 33050515, 2020). "The results suggest a synergistic inhibitory effect of MAPK4 knockout and PARP1 inhibitor on tumor growth in vivo." (PMID 32711558, 2020). "Having H&E as gold standard and using immunohistochemistry for quantification, we demonstrated that the overexpression of PARP1 is distinctly higher in these tumor masses compared to the normal tissue around them." (PMID 32636416, 2020). "For mouse genetic studies on the impact of PARP1 in both tumor suppression and oncogenesis, different methodologies and physiological context have shown differing results." (PMID 33231937, 2020). "Another example of tumor suppressor is the Poly (ADP-ribose) Polymerase 1 (PARP1) that plays a key role in DNA-damage repair, transcriptional regulation, chromatin remodeling, cell signaling and cell death." (PMID 33255335, 2020). "Concerning PARP1, its up-regulation has been reported in multiple cancers, while its inhibition has the capacity to suppress angiogenesis, metastasis, and tumor-induced inflammation." (PMID 32245130, 2020).
tumor (continued). "When tumour pathology was assessed, Parp1−/− cRb−/− RasV12 tumours showed lower phospho-histone H3 staining than Parp1+/+ cRb−/− RasV12 tumours, a finding that suggests a decreased proliferation rate in the former." (PMID 33050515, 2020). "C-MET inhibition enhances chemosensitivity of human EOC cells, and importantly, blocking c-Met-mediated PARP1 phosphorylation enhances anti-tumor effects of PARPis." (PMID 33213473, 2020). "In a subcutaneous pancreatic ductal adenocarcinoma model, in vivo tumor uptake was enhanced upon radiation, confirming radiation-induced PARP1 overexpression." (PMID 32640708, 2020). "Selective PARP-1 inhibitors can not only be used as radiotherapy and chemotherapy sensitizers to enhance anti-tumor efficacy, but also would mitigate toxicities arising from cross-inhibition of PARP-2." (PMID 32373627, 2020). "Small molecule inhibitors of PARP1 and PARP2 act in BRCA-mutant and Homologous recombination-deficient (HRD) tumours, probably through the mechanistic framework of synthetic lethality, although there are several theories for the exact mechanism of action." (PMID 32494876, 2020). "HR deficient tumor cells such as BRCA- mutated ones, relies on the other DNA repair pathways and especially PARP1 and PARP2 enzymes activity in order to survive." (PMID 32276534, 2020). "In tumor cells, PARP-1 can prevent cells from apoptosis by cleaving DNA-damage and, thus, inhibiting cell death." (PMID 33339368, 2020). "This activation of PARP-1 has been described as one of the therapeutic actions against different tumor cells." (PMID 33092171, 2020). "Our results show that genetic ablation of Parp1 extends the survival of Rb-null embryos and delays the development of pRb-dependent tumours." (PMID 33050515, 2020). "Successful induction of apoptosis in tumor cells was estimated with Western blot for PARP1, a typical apoptotic marker." (PMID 32033490, 2020). "We also tested the correlation of expression PARP2 with survival and tumour stages and found a positive correlation in only 2 datasets with lower effect respect to PARP1." (PMID 32103589, 2020). "This study investigated the therapeutic potential of combining niraparib, a highly selective PARP1/2 inhibitor, with anti-PD-1 immune checkpoint inhibitors in preclinical tumor models." (PMID 30755715, 2019). "PARP-1 is a nuclear enzyme that regulates DNA repair resulted ability to proliferate tumor cells even in the presence of DNA break via upregulation of DNA repair mechanism through PARP-1." (PMID 31450709, 2019). "Although PARP1 constitutes a promising target in the treatment of tumors harboring deficiencies in BRCA-mediated HR, some tumor cells acquire therapy-resistance and survive, resulting in disease relapse." (PMID 31615159, 2019). "Classical studies demonstrate that Parp1–/– mice develop spontaneous tumor formation in various tissues including the mammary gland and are prone to carcinogen-induced neoplastic growth." (PMID 30459355, 2019). "Both western blot analysis and IHC assay confirmed that overexpression of ZEB1 significantly abrogated the gemcitabine-induced elevation of p-γH2AX and cleaced-PARP-1 in ROCK2-deletion tumor." (PMID 31783584, 2019). "There are several ongoing clinical trials combining PARP-1 inhibitors with radiation therapy for which our study provides mechanistic insights into the tumor-killing activity observed in the clinic." (PMID 31273204, 2019). "Mechanistically, MZF1 regulates the expression of proline synthetic genes, while MZF1‐AS1 interacts with PARP1 to enhance its interaction with E2F1, resulting in upregulation of MZF1 and other oncogenic genes associated with tumor progression." (PMID 31592410, 2019). "The response rate and progression‐free survival were higher in patients with high PARP1 tumor expression, confirming their preclinical findings." (PMID 31131495, 2019).
tumor (continued). "Veliparib is a potent inhibitor of PARP1/2, which was demonstrated in 2007 to have high anti-tumor efficacy when combined with DNA alkylating agents, such as temozolomide and irradiation." (PMID 31109041, 2019). "To further explore the biological alterations associated with the PARP1 expression status, we compared the whole‐genome expression profiles of the ‘PARP1‐high’ (N = 89) and ‘PARP1‐low’ (N = 135) primary tumor samples in the TCGA data set." (PMID 31131495, 2019). "The novel role of HMGA2 in enhancing PARP1 PARylation activity and reducing efficacy of olaparib in blocking PARP1 function and PARP1 DNA trapping is expected to impact on tumor cell viability." (PMID 30289618, 2019). "Although PARP1 constitutes a promising target in the treatment of tumors harboring deficiencies in BRCA1/2—mediated homologous recombination (HR), some tumor cells survive, resulting in disease relapse." (PMID 31615159, 2019). "Synthetic lethality induced by PARP1 inhibition has emerged as a promising method for targeting tumor cells with defective homologous recombination pathways." (PMID 30551210, 2019). "To investigate the relationship between hypoxia and PARP-1 expression in vivo in tumor xenografts, we compared PARP-1 signal intensity with EF5 staining, which is known to accumulate in regions of clinically relevant hypoxia." (PMID 30389822, 2019). "PARP1 also regulates the c-Jun N-terminal kinase (JNK) pathway, which is implicated as a driver of both tumor development and treatment response." (PMID 31109041, 2019). "The loss of PARG activity in BRCA2-deficient tumours treated with potent PARP-1 inhibitors is sufficient to restore PAR formation and rescue PARP-1 downstream signaling." (PMID 30862789, 2019). "Here, we show that poly (ADP-ribose) polymerase 1 (PARP1) and ataxia-telangiectasia-mutated (ATM) kinase, two tumor suppressors, are important regulators in mitochondrial alterations induced by UVB." (PMID 31861350, 2019). "PARP1 expression was assessed in 107/124 (86.3%) of tumor samples, and it was positive in 20/107 (18.7%) of the tumors." (PMID 31540486, 2019). "In contrast, other recent reports raised the possibility of PARP-1 as a pro-tumorigenic factor, as many tumor types expressed high levels of PARP-1, and its over-expression often correlates with disease progression." (PMID 31877876, 2019). "The results showed that PARP1 mRNA expression was much higher in HCC tissues than that in adjacent non-tumor tissues." (PMID 29776974, 2018). "Our experiments also showed that PARP1 mutation can be tolerated in certain BRCA1 mutant, PARPi-sensitive tumour cells." (PMID 29748565, 2018). "The inhibition of PARP-1 inhibits the proliferation of cultured tumor cells and tumor growth in xenograft models." (PMID 30487462, 2018). "Combined, this suggests that PARP-1 inhibition is mechanistically involved in the RAPTA-T-induced changes on the tumor vasculature." (PMID 29980753, 2018). "Drugs targeting the poly-(ADP-ribose) polymerase (PARP) enzymes PARP1 and PARP2 cause synthetic lethality in tumour cells with homologous recombination (HR) defects, including those with loss-of-function mutations in the BRCA1 or BRCA2 tumour suppressor genes." (PMID 29748565, 2018). "By tumor immunostaining analysis, we found a linear correlation between tumor derived PARP-1 expression decrease and enhanced pericyte vascular coverage in RAPTA-T treated tumors." (PMID 29980753, 2018). "PARP1 also plays important role in mesenchymal–epithelial transition (EMT) which promotes tumor metastasis." (PMID 29776974, 2018). "Collectively these results suggest that Z-DAN-11 involves both the extrinsic and intrinsic pathway causing mitochondrial damage, activation of caspases leading to PARP1 cleavage, DNA damage, and eventually tumor cell apoptosis." (PMID 29670107, 2018).